SYK (spleen associated tyrosine kinase)
Diseases named in the same sentence as SYK in open-access papers (continued):
Sharing a sentence is not in itself a finding about the gene and the disease.
rheumatoid arthritis (25 papers, 2013 to 2025). A chronic, systemic autoimmune disorder characterized by inflammation in the synovial membranes and articular surfaces. "SYK signaling, for example, has been implicated in certain forms of cancer, rheumatoid arthritis, and other inflammatory diseases." (PMID 39601545, 2025). "Fostamatinib is a spleen tyrosine kinase (SYK) inhibitor employed in the treatment of rheumatoid arthritis and immune thrombocytopenia purpura." (PMID 35052711, 2021). "This drug is a spleen tyrosine kinase (SYK) inhibitor approved for the treatment of rheumatoid arthritis and immune thrombocytopenic purpura and has also been granted orphan drug status." (PMID 32872158, 2020). "It is noted that SYK is considered as a possible target for rheumatoid arthritis treatment because of its biologic roles within bone metabolism." (PMID 32496000, 2020). "We used a previously published randomized controlled trial (Oral SyK Inhibition in Rheumatoid Arthritis-1) to assess its performance in comparison to a standard method treating patients purely as responders or non-responders." (PMID 27338084, 2016). "To illustrate the benefits of such an approach, we use the Oral SyK Inhibition in Rheumatoid Arthritis (OSKIRA-1) study and consider ACR and DAS28 end points." (PMID 27338084, 2016). "The SYK inhibitor R406, currently in clinical development for rheumatoid arthritis, can induce caspase-mediated cell death of retinoblastoma cells in culture." (PMID 24906597, 2014). "Given the clinical efficacy of Bcell depletion in the treatment of rheumatoid arthritis and multiple sclerosis, pharmacological modulation of Bcells using orally active small molecules that selectively target SYK presents an attractive alternative therapeutic strategy." (PMID 24286216, 2013). "Atherosclerosis complicates chronic inflammatory diseases, such as rheumatoid arthritis and systemic lupus erythematosus, suggesting that a shared physiological pathway regulates inflammatory responses in these diseases wherein spleen tyrosine kinase (SYK) is involved." (PMID 37520709, 2023). "Currently, through research on these activation mechanisms, kinases, such as JAK, MAPK, SYK, PI3K, NF-κB, and BTK, are being recognized as major targets for the development of rheumatoid arthritis treatments." (PMID 37623223, 2023). "The present study collectively suggests that dual JAK + SYK inhibition with selective, potent and orally bioavailable small molecules could complement the current arsenal of tools in development for the treatment of rheumatoid arthritis and likely other inflammatory and autoimmune disorders." (PMID 26653844, 2015). "Tyrosine kinase-inhibitors (TKI), including Spleen tyrosine kinase (SYK) (fostamatinib) and Janus kinases (tofacitinib), are two novel oral therapies that have demonstrated good short-term clinical responses in active rheumatoid arthritis patients." (PMID 38276107, 2024).
B-cell lymphoma (23 papers, 2013 to 2025). "PDE4B, an isoform of PDE4, is highly expressed in refractory DLBCL patients and the anticancer effect of PDE4 inhibitors has been confirmed in B-cell lymphoma in vitro and in vivo, associated with repression of the SYK/AKT/mTOR pathway." (PMID 34833935, 2021). "In addition, a recent study demonstrated the role of SYK to promote the survival of MYD88-mutated B-cell lymphoma cells in vitro." (PMID 33921415, 2021). "Indeed, increased activity or overexpression of SYK is associated with worse prognosis of patients with acute myeloid leukemia, chronic lymphocytic leukemia, or T- or B-cell lymphoma, while SYK knockdown or inhibition induces apoptosis both in vitro and in vivo." (PMID 29137391, 2017). "Inhibition of additional proteins in the BCR pathway such as SYK have shown pre-clinical efficacy when combined with emavusertib in B-cell NHL." (PMID 37954584, 2023). "Active SYK is expressed in acute or chronic lymphocytic leukemia (CLL) and in subgroups of EBV‐associated B‐cell lymphoma." (PMID 37506139, 2023). "The combination of ibrutinib and SYK inhibitors is synergistically lethal to MyD88 mutant B cells, which provides new ideas for the clinical treatment of B‐cell lymphoma." (PMID 37506139, 2023). "SYK inhibitors showed in vitro and in vivo activity against B-cell lymphomas and various other hematological neoplasias." (PMID 33363034, 2020). "Responses to the SYK inhibitor HMPL-3 have also been observed across multiple B-cell lymphomas, including WM30." (PMID 32005797, 2020). "Targeted SYK therapy has been advocated in various types of B-cell lymphomas, and specific inhibitors for its kinase activity are already approved such as R406, fostamatinib, opening avenues for testing targeted treatment in SCLC." (PMID 24564859, 2013). "SYK is known for its role in B cell lymphoma mediated signalling." (PMID 38565869, 2024). "Fostamatinib (R788) is the first SYK inhibitor tested in clinical phase I/II study for the treatment of B-cell lymphomas, and shows effective therapeutic action, indicating that SYK inhibition could be a novel therapeutic approach in cancer treatment." (PMID 36568669, 2022). "In Burkitt lymphoma cells, the SYK target-enriched signaling pathways included molecules that could play a role in SYK pro-oncogenic function in B-cell lymphomas." (PMID 33670716, 2021). "Spleen tyrosine kinase (SYK) controls B-cell receptor (BCR) signal initiation and amplification, which promotes B-cell lymphoma progression." (PMID 33712015, 2021). "Therefore, BTK could be crucial for SYK pro-oncogenic function in B-cell lymphomas." (PMID 33670716, 2021). "We tested two BCR signaling inhibitors (SYK inhibitor R406 and IKKβ inhibitor BMS345541) in three B cell lymphoma cell lines derived from GCB-DLBCL (SUDHL4, CD10 +/BCL6 +), ABC-DLBCL (SUDHL8, CD10−/BCL6−) and primary effusion lymphoma (BCBL1, CD10−/BCL6−)." (PMID 26639163, 2015). "The positive-control B-cell lymphoma cell line SU-DHL-4 revealed a high SYK expression, while the negative-control T-cell lymphoma cell line SUP-T1 was SYK-negative." (PMID 33435587, 2021). "The simultaneous inhibition of SYK and BET showed enhanced anti-proliferative effects, as well as inducing a distinct combination-specific gene expression profile, suggesting SYK and BET inhibition as a promising combination in the treatment of B-cell lymphoma." (PMID 36230614, 2022). "However, SYK inhibitors have not yet been able to gain clinical importance in the treatment of B-cell lymphomas." (PMID 33363034, 2020).
retinoblastoma (23 papers, 2012 to 2025). A malignant tumor that originates in the nuclear layer of the retina. "The high SYK expression preceding early cone precursor maturation and its loss during late maturation implies that high-level SYK expression is a retinoblastoma cell-of-origin-specific feature." (PMID 40767624, 2025). "Whereas SYK was previously implicated in retinoblastoma genesis and proposed to be induced in response to pRB loss, its expression was not previously reported in developing fetal retina." (PMID 40767624, 2025). "GS-9876 treatment suppressed the proliferative response to pRB knockdown at all concentrations from 1.0 to 5.0 μM, consistent with the notion that cone precursor intrinsic SYK activity contributes to the proliferative response to pRB loss and is retained in retinoblastoma cells." (PMID 40767624, 2025). "Targeting SYK with small molecule inhibitors induces retinoblastoma tumor cell death in vitro and in vivo." (PMID 40502639, 2025). "In the context of retinoblastoma, aberrant acetylation at the SYK promoter enhances its expression, promoting oncogenic signaling and tumor cell survival." (PMID 41150792, 2025). "Overexpression of the oncogene Spleen Tyrosine Kinase (SYK), was associated with acetylation of histone H3K9/14ac, located at the promoter of this gene, in retinoblastoma cases." (PMID 41150792, 2025). "They reported that the proto-oncogene SYK is upregulated in retinoblastoma and is required for tumor cell survival." (PMID 40502639, 2025). "LMPs can downregulate SYK and induce retinoblastoma cell death, as further supported by the immunohistochemical results of SYK expression." (PMID 36132125, 2022). "SYK protein was found at higher levels in human retinoblastoma in situ xenografts and cell lines than in human fetal retina." (PMID 36132125, 2022). "A multi-omic study showed that epigenetic changes, including upregulation of SYK, cooperate with RB1 loss to support retinoblastoma tumor progression." (PMID 35433448, 2022). "Plotting the expression of genes known to be associated with retinoblastoma development, such as MDM2, DEK, SYK and HELLS, confirmed their upregulation in RB1ko when compared to RB1wt and RB1het and in the tumor specimens." (PMID 35565295, 2022). "The SYK inhibitor BAY-61-3606 led to apoptosis in retinoblastoma cell lines and resulted in antitumor effects after subconjunctival administration in orthotopic xenografts." (PMID 35433448, 2022). "ChIP-on-chip analysis revealed increased histone activation modifications (H3K4me3 and K3K9/14Ac) at the SYK promoter, whereas the histone repression marker (H3k9me3) was unchanged in human retinoblastoma in situ xenografts and cell lines." (PMID 36132125, 2022). "Transcriptome profiles revealed gradual development of a retinoblastoma expression signature in RB1ko with upregulation of proliferation-associated genes and retinoblastoma-related oncogenes such as DEK, SYK and HELLS." (PMID 35565295, 2022). "For 24 h, treatment of human retinoblastoma cells with 20μg/ml LMPs was carried out and the expression of SYK protein was analyzed by Western blot." (PMID 36132125, 2022). "One of the hallmarks of retinoblastoma is the epigenetic deregulation of the SYK oncogene which is required for tumorigenesis." (PMID 34315877, 2021). "Treatment of genetic retinoblastoma model with synthetic SYK inhibitor resulted in dramatic suppression of disease progression and prolongation of survival." (PMID 34359636, 2021). "Although the dependence on E2Fs is still unclear, human retinoblastoma cells highly express a proto-oncogene spleen tyrosine kinase (SYK) and depend on its expression for survival." (PMID 34359636, 2021). "In two other pediatric cancers, retinoblastoma and Ewing sarcoma, SYK promotes tumor cell survival and SYK inhibition, using small molecule inhibitors, was identified as a promising treatment option for these diseases." (PMID 30744170, 2019).
retinoblastoma (continued). "Specifically, it was shown that the SYK gene is epigenetically deregulated and expressed at high levels in retinoblastoma thus preventing programmed cell death through MCL126." (PMID 27739525, 2016). "The preclinical candidate SYK inhibitor BAY-61-3606 was efficacious in blocking proliferation of human orthotopic retinoblastoma xenografts in vivo." (PMID 24906597, 2014). "Since R406 is the SYK inhibitor farthest along in clinical development (Phase 3), and therefore the most likely compound to be tested clinically against retinoblastoma, we decided to focus upon its evaluation." (PMID 24906597, 2014). "Recently, characterization of the genetic and epigenetic landscapes of retinoblastoma revealed increases in expression of the proto-oncogene spleen tyrosine kinase (SYK)." (PMID 24906597, 2014). "Despite the failing of R406 as a retinoblastoma clinical candidate, SYK remains a promising target as there are many other small molecule SYK inhibitors with diverse physiochemical properties to evaluate as retinoblastoma therapeutics." (PMID 24906597, 2014). "Recent studies characterizing the genomic and epigenomic landscape of retinoblastoma identified spleen tyrosine kinase (SYK) as a promising candidate for targeted therapy." (PMID 24906597, 2014). "The purpose of this study was to conduct preclinical testing of the SYK antagonist R406 to evaluate it as a candidate for retinoblastoma treatment." (PMID 24906597, 2014). "The efficacy of the SYK antagonist R406 delivered locally in a human orthotopic xenograft mouse model of retinoblastoma was tested." (PMID 24906597, 2014). "At least one of those epigenetically deregulated genes (SYK) is required for retinoblastoma tumor cell survival in vivo." (PMID 23765217, 2013). "For example, the SYK gene was found to be epigenetically upregulated in virtually all human retinoblastomas and it is required for tumor cell survival." (PMID 23765217, 2013). "A recent study showed elevated expression of SYK in primary retinoblastoma tissue and retinoblastoma cell lines and BAY 61-3606 induced cell death in these samples with a concomitant increase in active Caspase-3." (PMID 23304241, 2012). "However, given potential SYK inhibitor off-target effects, validation of the role of SYK in retinoblastoma initiation will require gene ablation studies." (PMID 40767624, 2025). "Also, F pharmacologic inhibition of SYK induces apoptosis in retinoblastoma cells, underscoring its potential as a therapeutic target." (PMID 41150792, 2025). "(H) Model of SYK expression in cone maturation and retinoblastoma development." (PMID 40767624, 2025). "In addition to accelerating apoptosis of retinoblastoma cells, Lenti-SYK-9 effectively removed SYK from retinoblastoma cell lines." (PMID 36132125, 2022). "Inhibiting SYK with a small molecule inhibitor caused degradation of MCL1 and caspase mediated cell death in retinoblastoma cells in vitro and in vivo and may be a drug target for retinoblastoma." (PMID 29124525, 2017). "The spleen associated tyrosine kinase (SYK) is widely overexpressed in human retinoblastoma because of altered epigenetic regulation, and this kinase activates AKT in diffuse large B-cell lymphomas, but their relationship in retinoblastoma is unclear." (PMID 28445155, 2017). "Furthermore, in retinoblastoma cells, ubiquitin-like, containing PFD and RING finger domains 1 (UHRF1) and helicase, lymphoid specific (HELLS) are overexpressed, which is linked to epigenetic activation of SYK." (PMID 34359636, 2021). "In the present review, we described the latest innovations in retinoblastoma immunotherapy targeting GD2, PD-1, B7H3, EpCAM and SYK." (PMID 36132125, 2022). "Transcriptome analysis of RB1 knockout organoids and primary retinoblastoma revealed gain of a retinoblastoma expression signature in the organoids, characterized by upregulation of RBL1 (p107), MDM2, DEK, SYK and HELLS." (PMID 35565295, 2022).
retinoblastoma (continued). "The loss of SYK protein and RNA expression with cone maturation is consistent with the lack of SYK in cones of normal retina adjacent to retinoblastoma tumors and implies that SYK is a defining feature of the human early cone precursor state." (PMID 40767624, 2025). "We further found that cone precursors highly express SYK, an oncoprotein previously detected in human retinoblastomas and RB1-null retinal organoids but not in healthy tumor-associated retina." (PMID 40767624, 2025). "Although SYK was consistently immunonegative in non-neoplastic lesions and pseudo retinoblastoma eyes, conversely, it was histologically immunopositive in any RB eyes." (PMID 36132125, 2022). "As a positive control for this study, we stained for the proto-oncogene spleen tyrosine kinase, SYK (data not shown), previously identified to be expressed in primary retinoblastomas." (PMID 26379276, 2015). "Though not expressed in normal human retinas, SYK was found to be upregulated in 100% (82/82) of the retinoblastoma samples and SYK was shown to be required for retinoblastoma cell survival." (PMID 24906597, 2014). "We examined all feasible delivery routes and formulations for the SYK inhibitor R406 and found that none achieved an intraocular exposure needed to induce retinoblastoma cell death." (PMID 24906597, 2014). "The upregulation of SYK found in virtually all human retinoblastomas was not evident in mouse retinoblastomas nor was upregulation of MCL1." (PMID 23765217, 2013). "Furthermore, the epigenetic landscape in mouse retinoblastoma was significantly different from human tumors and some pathways that are candidates for molecular targeted therapy for human retinoblastoma such as SYK or MCL1 are not deregulated in GEMMs." (PMID 23765217, 2013). "In addition, epigenetic alterations may drive retinoblastoma formation by inducing histone H3K4 trimethylation and H3K9/H3K14 acetylation of the spleen tyrosine kinase (SYK) oncogene promoter and activate its expression, which is required for tumor cell survival." (PMID 32366932, 2020). "Interestingly, we found that SYK, a gene that is epigenetically upregulated in human retinoblastoma and is required for retinoblastoma survival, is not epigenetically deregulated in mouse retinoblastoma." (PMID 23765217, 2013).